HIF1A (hypoxia inducible factor 1 subunit alpha)
Diseases named in the same sentence as HIF1A in open-access papers (continued):
Sharing a sentence is not in itself a finding about the gene and the disease.
apical periodontitis (2 papers, 2018 to 2025). "Our findings suggest that HIF-1α might be a potential therapeutic target for apical periodontitis." (PMID 29654284, 2018).
asthenozoospermia (2 papers, 2024 to 2025). "Health semen and asthenozoospermia (astheno) semen were incubated with hypoxia-inducible factor-1α (HIF-1α) interferents, i.e., lificiguat (YC-1) or cobalt chloride (CoCl2), respectively." (PMID 38605082, 2024).
autoimmune hepatitis (2 papers, 2024). Hepatitis caused by autoantibodies. "Similar results were observed in the toxic mouse model of CLD, while in CLD due to autoimmune hepatitis in mice, HIF-1α mRNA levels were comparable to the control group." (PMID 38338821, 2024). "Intrahepatic HIF-1α mRNA expression was markedly increased in rodents with a systemic infection with (ACLF) and without CLD caused by autoimmune hepatitis, while CLD itself did not influence the intrahepatic HIF-1α mRNA level." (PMID 38338821, 2024). "High expression of AHRR (AHR repressor) and HIF-1α inhibits AHR signaling in Th17 cells and regulatory T cells (Tregs) in autoimmune hepatitis (AIH)." (PMID 37692495, 2024).
autoimmune myocarditis (2 papers, 2022 to 2024). Autoimmune myocarditis is an autoimmune disease that affects the heart. "In experimental autoimmune myocarditis (EAM) model at different phases, scRNA-seq identified 26 cell subtypes among 34665 cells and found that Hif1a contributes to the inflammatory response mainly through the regulation of macrophage and T-helper 17 cells." (PMID 36226312, 2022).
autosomal dominant polycystic kidney disease (2 papers, 2012 to 2024). Autosomal dominant form of polycystic kidney disease. "Additionally, regarding HIF-1α mRNA concentrations in serum, significantly higher values have been noted in patients with autosomal dominant polycystic kidney disease." (PMID 39748872, 2024). "In human autosomal dominant polycystic kidney disease (ADPKD) HIF is also activated, but follows the “physiological” expression pattern of tubular HIF-1α and peritubular HIF-2α." (PMID 22299048, 2012).
bacterial pneumonia (2 papers, 2018 to 2019). Acute infection of the lung parenchyma caused by bacteria (e.g., Streptococcus pneumoniae, Haemophilus influenzae, Chlamydia pneumoniae, Mycoplasma pneumoniae, and Legionella pneumophila). "Overexpression of hypoxia-inducible factor-1 alpha (HIF-1α) in MSCs significantly enhanced survival of engrafted MSCs and remarkably increased their therapeutic effects in the Escherichia coli model of bacterial pneumonia." (PMID 31191672, 2019). "The current study investigated the effects of stabilizing HIF-1α on the therapeutic capacity of MSCs in an experimental mouse model of bacterial pneumonia." (PMID 29780805, 2018). "For acute inflammatory processes, such as lung injury due to bacterial pneumonia, even transient stabilization of HIF-1α can lead to significant beneficial outcomes as we observed." (PMID 29780805, 2018). "In summary, stabilization of HIF-1α in MSCs, with the use of AKB-4924, significantly boosts MSC-derived therapeutic capacity in an E. coli model of bacterial pneumonia." (PMID 29780805, 2018).
bone sarcoma (2 papers, 2018 to 2023). A sarcoma that arises from the bone. "A recent meta-analysis of 16 studies (5 in STS) evaluating the prognostic significance of HIF-1α in STS and bone sarcomas found high expression was associated with higher rates of metastases, poor OS and poor DFS." (PMID 29235571, 2018).
brain glioma (2 papers, 2024 to 2025). A malignant glioma that involves the brain. "Thus, for example, when testing is based on HIF-1α, a person with a positive test result has a 95.74% probability of having brain glioma." (PMID 40429943, 2025). "This allowed potential specific relationships to be identified between levels of the HIF-1α, ANG-2, and IL-1β proteins in brain glioma patients." (PMID 40429943, 2025). "For each tested protein (HIF-1α, ANG-2, and IL-1β), an increase in concentration implies an increase in the chances of developing brain glioma." (PMID 40429943, 2025). "In this work, matrix SPRi biosensors are used as a new analytical method to examine the levels of selected proteins (HIF-1α, ANG-2, and IL-1β) in plasma and tissue homogenates from patients with diagnosed brain glioma." (PMID 40429943, 2025).
bronchiolitis obliterans (2 papers, 2019 to 2021). "We hypothesized that bronchiolitis obliterans (BO) after lung transplantation is associated with hypoxia-inducible factor-1α (HIF-1α)." (PMID 30696477, 2019).
Candida infection (2 papers, 2020). "Promoting HIF‐1α stabilisation with the hydroxylase inhibitor CoCl2 promoted fungal death in vitro (human macrophages) and in vivo (mouse) indicating a therapeutic potential for HIF‐1α manipulation in candida infection." (PMID 32633061, 2020).
carcinoids (2 papers, 2021 to 2022). "HIF-1α is a well-described mediator of the hypoxic response in carcinoid tumors, responsible for regulating genes critical for tumor cell survival in low oxygen conditions, including CAIX and nuclear factor kappa B transcription factor (NF-κB)." (PMID 34316328, 2021). "Overexpression of hypoxia-inducible factor (HIF-1α), histone deacetylase (HDAC), and carbonic anhydrase IX (CAIX), as well as constitutive activation of the Akt/NF-kB pathway, have been implicated in carcinoid tumorigenesis." (PMID 34316328, 2021). "In the available tumoural tissue samples, hypoxia was assessed by evaluating HIF-1α positivity by IHC staining (39/53 carcinoids, 19 left-sided and 20 right-sided tumours, 2 cases were not evaluated)." (PMID 36233825, 2022).
carcinoma of the tongue (2 papers, 2013 to 2025). "The objective of this study was to investigate whether the expression of HIF-1α in tongue carcinoma was associated with established clinicopathological features." (PMID 23599780, 2013). "The mRNA levels of HIF-1α were measured in 45 fresh, paired samples of tongue carcinoma and corresponding adjacent normal tissues using quantitative RT-PCR (qRT-PCR)." (PMID 23599780, 2013). "Compared with paired normal tissues, HIF-1α mRNA levels were significantly increased in carcinoma of the tongue." (PMID 23599780, 2013). "The aim of this study was, therefore, to verify the role of HIF-1α expression in carcinoma of the tongue, to evaluate its correlation with clinicopathological features and to determine its value as a prognostic marker." (PMID 23599780, 2013). "In this study, increased expression of HIF-1α was observed in more advanced stages of tongue cancer, which indicates the critical role of HIF-1α in tongue carcinogenesis." (PMID 23599780, 2013). "In agreement with previous reports, this study showed that HIF-1α expression correlated with overall survival, and disease-free survival, of patients with tongue carcinomas." (PMID 23599780, 2013). "Tumour specimens from 120 patients with histologically-proven, surgically-treated tongue carcinoma were examined by immunohistochemical staining for expression of HIF-1α." (PMID 23599780, 2013). "A positive correlation was found between the mRNA level of HIF-1α and the pathological differentiation grade of tongue carcinomas." (PMID 23599780, 2013). "Nuclear staining of HIF-1α was detected in 75% (90/120) tongue carcinoma specimens." (PMID 23599780, 2013). "The aim of this study was to examine the role of HIF-1α signalling in tongue carcinoma progression." (PMID 23599780, 2013). "Overexpression of HIF-1α could be an indicator of poor prognosis in carcinoma of the tongue." (PMID 23599780, 2013). "This suggests that HIF-1α may play an important role in the progression of tongue carcinoma." (PMID 23599780, 2013). "The actual role of HIF-1α in tongue carcinoma progression, however, remains unclear." (PMID 23599780, 2013). "PX‐478, a hypoxia‐inducible factor‐1α (HIF‐1α) inhibitor, and BPR0C261, a microtubule‐disrupting agent, were administrated into tumour‐bearing mice established using murine MTCQ1 tongue cancer cells through intraperitoneal injection and oral gavage, respectively." (PMID 39757131, 2025).
cholesteatoma (2 papers, 2018 to 2021). A pathologic process characterized by the proliferation of keratinizing squamous epithelium resulting in the accumulation of keratin and cells in the middle ear and/or mastoid. "In this study, we have provided evidence that HIF‐1α, act as hypoxic-associated molecule is highly expressed in human cholesteatoma tissues." (PMID 34522167, 2021). "Herein, we found that culture of cholesteatoma keratinocytes isolated from cholesteatoma tissues under hypoxic conditions caused a concentration-dependent promotion of keratinocyte proliferation and increased HIF-1α expression under hypoxia conditions." (PMID 34522167, 2021). "Results showed that the protein expression of HIF-1α in cholesteatoma tissues was significantly higher than that in the normal skin (P<0.05)." (PMID 34522167, 2021). "HIF-1α expression in cholesteatoma tissue was remarkably upregulated relative to the normal skin according to the results of the immunofluorescence experiments." (PMID 34522167, 2021). "Next, we performed a co-stained of intrinsic hypoxia marker HIF-1α and a keratinocyte marker Pan-keratin in the cholesteatoma samples, and demonstrated that the staining of HIF-1α and Pan-keratin was present in cytoplasm." (PMID 34522167, 2021). "In cholesteatoma tissue, HIF-1α was obviously expressed in the cytoplasm of the basal and parabasal cell layers." (PMID 34522167, 2021). "In addition, we observed a co-expression of Pan-keratin and HIF-1α in the epithelium of cholesteatoma, strongly suggesting that HIF-1α is upregulated in cholesteatoma keratinocytes." (PMID 34522167, 2021). "However, studies on HIF-1α expression in cholesteatoma and its relationship with the pathological changes such as cholesteatoma keratinocyte proliferation on one hand, and with the intrinsic signaling pathways on the other hand, have not been fully understood." (PMID 34522167, 2021). "Thus, hypoxia induced by CoCl2 treatment was critical in upregulating HIF‐1α protein expression in cholesteatoma keratinocytes." (PMID 34522167, 2021). "The proliferation and cellular HIF-1α, p-PDK1 and p‐Akt expression levels of cholesteatoma keratinocytes were assessed in vitro." (PMID 34522167, 2021). "The present study illustrated that hypoxia activates HIF‐1α and enhances cell proliferation through the PI3K-Akt pathways in cholesteatoma keratinocytes." (PMID 34522167, 2021).
chorioamnionitis (2 papers, 2023). A morphologic finding indicating inflammation of the fetal sac membranes. "Specifically, we predicted that EPO, EPOR, MLTR1, SIRT1, HIF1α and HIF2α alterations after chorioamnionitis (CHORIO) would reflect relative changes observed in human preterm infants." (PMID 37546540, 2023).
choriocarcinoma (2 papers, 2023 to 2025). An aggressive malignant tumor arising from trophoblastic cells. "Hsa-miR-21-5p acts as an oncogenic miRNA in this context by suppressing HIF1AN, thus indirectly activating the HIF1A/VEGF pathway and promoting tumorigenesis in choriocarcinoma under hypoxic conditions." (PMID 40362695, 2025).
choroidal melanoma (2 papers, 2024 to 2025). Malignant tumor of melanocytes of the choroid. "Meanwhile, ART has played a role in suppressing choroidal melanoma by regulating the HIF-1α/VEGF/PDGF pathway." (PMID 39525639, 2024).
Chronic colitis (2 papers, 2016 to 2024). A chronic inflammatory disease of the large intestine (colon, cecum and rectum). "Yet, in contrast to acute DSS exposure, where a reduced ILC1/ILC3 ratio in HIF-1α KO mice is protective, in the context of chronic colitis, loss of HIF-1α in NKp46+ cells and prolonged reduction in ILC1s are associated with intestinal fibrosis." (PMID 38876796, 2024). "Yet, in the context of chronic colitis, HIF-1α in ILC1s counteracts excessive recruitment of proinflammatory neutrophils and Ly6Chi macrophages during chronic colitis, whereas loss of HIF-1α in NKp46+ ILCs results in increased intestinal fibrosis." (PMID 38876796, 2024). "Surprisingly, in the chronic colitis setting, HIF-1α KO mice show enhanced disease activity and intestinal damage, despite a reduction in proinflammatory ILC1s." (PMID 38876796, 2024). "Therefore, we concluded that loss of HIF-1α in NKp46+ cells promotes aberrant signaling circuits involving BMP, as well as integrin signaling and the mesenchymal cell compartment as a major signaling hub, which eventually contributes to aggravated chronic colitis." (PMID 38876796, 2024). "Yet, in the chronic colitis setting, the absence of HIF-1α in NKp46+ ILCs leads to an increased disease activity index and a concomitant rise in neutrophils and a Ly6Chigh macrophage subset that is considered as profibrotic." (PMID 38876796, 2024). "We found that in a model of chronic colitis, mice lacking the HIF-1α isoform in NKp46+ ILCs show a decrease in NKp46+ ILC1s in the colon mucosa, which resembles the phenotype during acute colitis." (PMID 38876796, 2024). "In contrast, in the current study, HIF-1α KO mice do not show a significantly reduced disease activity index after the first DSS exposure in the chronic colitis model." (PMID 38876796, 2024). "In chronic colitis, mice lacking the HIF-1α isoform in NKp46+ ILCs show a decrease in NKp46+ ILC1s but a concomitant rise in neutrophils and Ly6Chigh macrophages." (PMID 38876796, 2024). "However, more work is needed to understand the dynamic regulation of HIF-1α and HIF-2α in models of chronic colitis." (PMID 26812949, 2016).
chronic gastritis (2 papers, 2014 to 2025). Inflammation of the stomach that is chronic in nature. "The expression intensities of PI3K, p-Akt and HIF-1α were significantly increased in GC tissues compared with chronic gastritis tissues (each P<0.01)." (PMID 24765145, 2014). "The positive expression of PI3K, p-Akt and HIF-1α was predominantly localized in the cytoplasm of the GC tissue cells, but was not identified in the chronic gastritis cells." (PMID 24765145, 2014). "In the present study, specimens from 45 GC and 36 chronic gastritis patients were collected, and the correlations of PI3K, phosphorylated-Akt (p-Akt) and hypoxia-inducible factor-1α (HIF-1α) expression with the clinicopathological characteristics of GC were analyzed by immunohistochemistry." (PMID 24765145, 2014).
chronic granulomatous disease (2 papers, 2019 to 2022). Chronic granulomatous disease (CGD) is a rare primary immunodeficiency, mainly affecting phagocytes, which is characterized by an increased susceptibility to severe and recurrent bacterial and fungal infections, along with the development of granulomas. "This study demonstrates that thymosin β4 stabilizes HIF-1a to promote autophagy and up-regulate genes involved in tissue and mucosal barrier protection in chronic granulomatous disease." (PMID 31719116, 2019). "Moreover, HIF-1α stabilization in chronic granulomatous disease (CGD) has been demonstrated to improve infection resolution by promoting LC3-associated phagocytosis, a noncanonical autophagy pathway decisive in phagosome maturation and fungal killing." (PMID 36275017, 2022).
chronic hepatitis (2 papers, 2011 to 2017). An active inflammatory process affecting the liver for more than six months. "Later, stabilization of HIF-1α was noted in liver biopsy specimens obtained from patients with chronic hepatitis C26." (PMID 28112200, 2017).
chronic mountain sickness (2 papers, 2017 to 2022). A pathological condition resulting from chronic exposure to hypoxia at high altitude. "Moreover, in preclinical chronic mountain sickness, an hypermethylation of EGLN1 has been reported to diminish PHD2 expression and thereby enable transcription of HIF-1α." (PMID 36091390, 2022). "Although expression of hypoxia-inducible factor 1α (HIF-1α) and EPOR does not differ between chronic mountain sickness patients and control subjects, the expression of HIF-2α and EPO is higher in the bone marrow cells of chronic mountain sickness patients than in controls." (PMID 28703764, 2017).
Chuvash polycythemia (2 papers, 2013 to 2014). Chuvash erythrocytosis is a rare, genetic, congenital secondary polycythemia disorder characterized by increased hemoglobin, hematocrit and erythropoietin serum levels and normal oxygen affinity, which usually manifests with headache, dizziness, dyspnea and/or plethora. "However, in these studies, HIF-1α heterozygously deficient rats, patients with Chuvash polycythemia, and patients with a HIF-2α gain-of-function mutation had chronic pulmonary hypertension, and the structure of pulmonary arteries was likely to be remodeled." (PMID 23393065, 2013). "The most extensively studied patients are those with Chuvash polycythemia, who are homozygous for a hypomorphic allele of the VHL tumor suppressor, which impairs HIF-1α and HIF-2α degradation." (PMID 24201705, 2014).
colorectal adenoma (2 papers, 2013 to 2025). An adenoma that arises from the colon or rectum. "Meanwhile, at the protein level, the data obtained from The Protein Atlas showed a high expression of HIF-1α, similar to that reported in multiple studies that used paraffin-embedded samples, and a 66.7% higher expression in tumor tissue compared to 12–25% in colorectal adenomas." (PMID 40072116, 2025).
coronary artery calcification (2 papers, 2014 to 2023). Calcification of the coronary artery, used as a measure of coronary atherosclerosis, a risk factor for myocardial infarction. "Multivariate logistic regression analysis and ROC curves showed that HIF-1α can predict the presence and severity of coronary artery calcification." (PMID 24564828, 2014).
Coronary Artery Stenosis (2 papers, 2023). "We analyzed the associations of the whole blood RMRP, THRIL, and HIF1A expression levels with the SPECT SSS on the basis of the dipyridamole–thallium-201 scans of patients with a positive thallium stress test but without significant coronary artery stenosis." (PMID 37238718, 2023). "The results revealed an expression signature consisting of the upregulation of RMRP (p < 0.01) and downregulations of THRIL (p < 0.01) and HIF1A (p < 0.01) among patients with a positive thallium stress test and no significant coronary artery stenosis within 6 months after baseline treatment." (PMID 37238718, 2023).
cystic fibrosis (2 papers, 2016 to 2017). Autosomal recessive disorder caused by pathogenic variants in the CFTR gene (cystic fibrosis transmembrane conductance regulator), which encodes a chloride and bicarbonate channel expressed in epithelial cells, and follow the diagnosis criteria. "DCA and CDCA destabilised the transcription factor, Hypoxia Inducible Factor-1α (HIF-1α) in the immortalised bronchial epithelial cell line IB3-1 derived from a cystic fibrosis patient." (PMID 29383197, 2017).
dermatitis (2 papers, 2017 to 2023). An inflammatory process affecting the skin. "As compared with mice receiving PBS vehicle control, those that received PX-478, a selective HIF-1α inhibitor, had significantly reduced clinical skin disease (according to dermatitis score) at 20 weeks." (PMID 37526979, 2023). "Th17 cell-associated genes, (i.e., S100a8, CAMP, BATF, IL-23A, LCN2, and HIF-1α) highly expressed in Nfkbiz−/− mice with dermatitis, were downregulated after antibiotic treatments." (PMID 28740238, 2017).